HSD3B1 (hydroxy-delta-5-steroid dehydrogenase, 3 beta- and steroid delta-isomerase 1)
Description:
A bifunctional enzyme responsible for the oxidation and isomerization of 3beta-hydroxy-Delta(5)-steroid precursors to 3-oxo-Delta(4)-steroids, an essential step in steroid hormone biosynthesis. Specifically catalyzes the conversion of pregnenolone to progesterone, 17alpha-hydroxypregnenolone to 17alpha-hydroxyprogesterone, dehydroepiandrosterone (DHEA) to 4-androstenedione, and androstenediol to testosterone. Additionally, catalyzes the interconversion between 3beta-hydroxy and 3-oxo-5alpha-androstane steroids controlling the bioavalability of the active forms. Specifically converts dihydrotestosterone to its inactive form 5alpha-androstanediol, that does not bind androgen receptor/AR. Also converts androstanedione, a precursor of testosterone and estrone, to epiandrosterone. Expected to use NAD(+) as preferred electron donor for the 3beta-hydroxy-steroid dehydrogenase activity and NADPH for the 3-ketosteroid reductase activity (Probable).
Synonyms: HSDB3A; SDR11E1; 3BETAHSD; HSD3B; HSDB3
Tractability: Small molecule: a high-quality ligand is known; it belongs to a druggable protein family. Antibody: UniProt predicts a signal peptide or a membrane-spanning region. PROTAC: a small molecule that binds it is known.
Target class: Enzyme
Gene: Protein-coding gene on chromosome 1 (119,507,198 to 119,515,054, forward strand). Ensembl gene ENSG00000203857.
Subcellular location: Endoplasmic reticulum membrane; Mitochondrion membrane
Subcellular location (Human Protein Atlas): Endoplasmic reticulum; Nucleoli; Primary cilium; Cytokinetic bridge; Microtubules; Primary cilium transition zone
Pathways (Reactome):
Metabolism: Androgen biosynthesis; Glucocorticoid biosynthesis; Mineralocorticoid biosynthesis
Gene Ontology:
Molecular function: 3-beta-hydroxysteroid 3-dehydrogenase (NADP+) activity; 5-alpha-androstane-3-beta,17-beta-diol dehydrogenase (NADP+) activity; protein binding; 3-beta-hydroxy-Delta5-steroid dehydrogenase (NAD+) activity; steroid Delta-isomerase activity; alcohol dehydrogenase (NAD+) activity; oxidoreductase activity, acting on the CH-OH group of donors, NAD or NADP as acceptor
Biological process: progesterone biosynthetic process; androgen biosynthetic process; C21-steroid hormone metabolic process; estrogen biosynthetic process; steroid biosynthetic process
Cellular component: endoplasmic reticulum; mitochondrial inner membrane; mitochondrial intermembrane space; cytoplasm; endoplasmic reticulum membrane; smooth endoplasmic reticulum membrane; mitochondrial membrane
Genetic constraint (gnomAD): Loss-of-function variants: 11 observed, 11.18 expected, observed/expected ratio (o/e) 0.98, 90% interval 0.62 to 1.61. The upper end of that interval is the gene's LOEUF score, 1.61, which puts it in group 6 of 6, group 1 being the genes least tolerant of losing a copy. Missense variants: 490 observed, 473.32 expected, observed/expected ratio (o/e) 1.04, 90% interval 0.96 to 1.12. Synonymous variants: 217 observed, 193.06 expected, observed/expected ratio (o/e) 1.12, 90% interval 1 to 1.26.
Homologues: Orthologues: chimpanzee HSD3B1 (99% identical), macaque HSD3B1 (94% identical), dog HSD3B2 (80% identical), guinea pig Hsd3b1 (74% identical), rat Hsd3b2 (73% identical), rat Hsd3b1 (73% identical), mouse Hsd3b1 (72% identical), mouse Hsd3b2 (71% identical), mouse Hsd3b3 (71% identical), mouse Hsd3b6 (70% identical), mouse Hsd3b5 (69% identical), rat Hsd3b5 (69% identical), and 10 more. Paralogues in human: HSD3B2 (93% identical), HSD3B7 (37% identical), SDR42E1 (30% identical), SDR42E2 (28% identical), NSDHL (24% identical), TGDS (22% identical), GALE (20% identical), UXS1 (19% identical), GMDS (18% identical), GFUS (14% identical).
Diseases named in the same sentence as HSD3B1 in open-access papers:
HSD3B1 is named in the same sentence as 43 diseases in open-access papers, as found by Europe PMC text mining. Sharing a sentence is not in itself a finding about the gene and the disease. The quoted sentences say what the papers report.
prostate carcinoma (25 papers, 2018 to 2026). A carcinoma that arises from epithelial cells of the prostate gland. "For over twelve years, HSD3B1 has been studied in prostate cancer, where the adrenal-permissive allele is associated with enhanced extragonadal and intratumoral androgen synthesis, resistance to androgen deprivation therapies, and poor outcomes." (PMID 40565184, 2025). "Two SNPs in HSD3B1 previously associated with overall survival in advanced prostate cancer were associated with tumor extent at diagnosis and showed trend associations with metastasis-free survival." (PMID 39945744, 2025). "Retrospective studies have suggested an association of the HSD3B1 adrenal-permissive homozygous genotype with androgen deprivation therapy resistance in prostate cancer." (PMID 38506808, 2024). "About half of all men with prostate cancer inherit at least 1 copy of the adrenal-permissive HSD3B1 allele, which is associated with more rapid ADT resistance and poorer survival in men with nonmetastatic disease and low-volume (LV) metastatic disease." (PMID 39286977, 2024). "Although this is, to our knowledge, the largest, most racially diverse cohort to date investigating the association of the HSD3B1 genotype in men with prostate cancer, there are several limitations." (PMID 38506808, 2024). "In this cohort study of US veterans undergoing treatment for prostate cancer in the VA health care system who had undergone germline genotyping, we investigated the association of HSD3B1 genotype status with outcomes." (PMID 38506808, 2024). "This cohort study analyzes the association of HSD3B1 status with prostate cancer outcomes among patients in the Veterans Affairs Health System in the US." (PMID 38506808, 2024). "Is the adrenal-permissive HSD3B1 homozygous genotype associated with worse clinical outcomes in men with prostate cancer?" (PMID 38506808, 2024). "In this cohort study, we investigated the association of HSD3B1 genotype status with outcomes in a large cohort of men with prostate cancer who were receiving care in the VA health care system and underwent germline genotyping in the MVP." (PMID 38506808, 2024). "Half of all men with advanced prostate cancer (PCa) inherit at least 1 copy of an adrenal-permissive HSD3B1 (1245C) allele, which increases levels of 3β-hydroxysteroid dehydrogenase 1 (3βHSD1) and promotes intracellular androgen biosynthesis." (PMID 37966114, 2023). "Previous studies revealed there are two common germline missense-encoding alleles HSD3B1(1245A) and HSD3B1(1245C) in prostate cancer patients." (PMID 36647834, 2023). "These mechanistic data suggest a clinical pharmacologic strategy to counter the aggressive disease and poor clinical outcomes conferred by inheritance of the adrenal-permissive HSD3B1 allele, which commonly occurs in men with prostate cancer." (PMID 36647826, 2023). "Androgen biosynthesis enzyme 3β-hydroxysteroid dehydrogenase type 1 (3βHSD1) encoded by HSD3B1 has emerged as a potential driver for therapeutic resistance in prostate cancer." (PMID 36647834, 2023). "The findings provide insights into mechanisms underlying castration resistance in prostate cancer and reveal a potential strategy to circumvent therapeutic resistance in patients with homozygous HSD3B1(1245C) inheritance." (PMID 36647834, 2023). "The role of 3βHSD1 variation in prostate cancer arises predominantly from a germline missense-encoding variant (1245A→C) of the gene HSD3B1." (PMID 37435458, 2022). "In this epidemiological study, we confirmed that the alteration in the HSD3B1 gene that affected the progression of prostate cancer in clinical trials, is associated with increased risk of prostate cancer death in men diagnosed with metastatic disease." (PMID 33921650, 2021). "This prognostic study investigates the significance of missense polymorphism in the HSD3B1 gene among men treated with primary androgen-deprivation therapy or abiraterone for prostate cancer." (PMID 30794306, 2019).
prostate carcinoma (continued). "Supporting the broader relevance of this observation, our previously published prostate cancer cohort also showed CC genotype frequencies of 9–10% among Black and Asian patients, again supporting the potential role of HSD3B1 in hormone-driven cancer biology and cancer predisposition." (PMID 40565184, 2025). "Despite its limitations, this study is the first to investigate CYP17A1 and HSD3B1 polymorphisms in a Nigerian prostate cancer cohort, revealing population-specific genetic features that may inform biomarker development and precision oncology." (PMID 41023281, 2025). "Growing evidence demonstrates an association of HSD3B1 inheritance with prostate cancer outcomes." (PMID 38506808, 2024). "However, studies to date have not identified any profound associations between somatic genetic alterations and germline HSD3B1 in prostate cancer, and thus, a bias because of co-occurring somatic mutations is unlikely." (PMID 39286977, 2024). "In this cohort study of 5287 men with prostate cancer in the Million Veteran Program, the HSD3B1 adrenal-permissive homozygous genotype (compared with the adrenal-restrictive homozygous and heterozygous genotype) was associated with worse prostate cancer–specific mortality." (PMID 38506808, 2024). "We hypothesized that patients who were homozygous for the adrenal-permissive HSD3B1(1245C) allele would have worse prostate cancer–related survival outcomes." (PMID 38506808, 2024). "In addition to CYP17A1, another key rate-limiting androgen biosynthesis enzyme, 3β-hydroxysteroid dehydrogenase type 1 (3βHSD1) encoded by HSD3B1, has emerged as a potential driver for therapeutic resistance in prostate cancer." (PMID 36647834, 2023). "Additionally, we examined the cumulative effect of pre-specified alterations in the three critical androgen-regulating genes (including HSD3B1) and found that their combination predisposes to death from prostate cancer." (PMID 33921650, 2021). "Genetic mutation in HSD3B1 is identified to be associated with prostate cancer susceptibility." (PMID 32515122, 2020). "Recently, genetic polymorphism in HSD3B1 encoding 3β-hydroxysteroid dehydrogenase-1 has been shown to be associated with oncological outcome when treated with androgen-deprivation therapy (ADT) for prostate cancer." (PMID 30794306, 2019). "However, variant carriers of HSD3B1 among 99 men with castration-resistant prostate cancer showed distinctly better response to abiraterone therapy." (PMID 30794306, 2019). "We utilized these resources to investigate how germline HSD3B1 variant status impacts the somatic features, signaling pathways, and immune microenvironment in prostate cancers with the goal of further elucidating how HSD3B1 variant status may impact therapy response." (PMID 40282446, 2025). "Furthermore, in a study of over 5,200 men that also includes those with localized disease, adrenal-permissive HSD3B1 allele homozygosity is associated with a higher risk of prostate cancer death, thus making it the most common monogenic link to prostate cancer mortality." (PMID 39286977, 2024). "HSD3B1 genotype was obtained in 287 patients with LV disease treated with ADT + AR antagonist only in the phase III Enzalutamide in First Line Androgen Deprivation Therapy for Metastatic Prostate Cancer (ENZAMET) trial and was associated with clinical outcomes." (PMID 39286977, 2024). "Gain of function of this HSD3B1 variant, which has a global allelic prevalence of 0.69678, results in resistance to proteasomal degradation with the consequent accumulation of the enzyme and has been associated with a poor prognosis in patients with prostate cancer." (PMID 35563252, 2022). "This study confirmed the finding that HSD3B1 genetic variation may be associated with detrimental outcomes of ADT on prognosis in Japanese men with prostate cancer, augmenting the robustness of previous findings and suggesting universal significance among different ethnicities." (PMID 30794306, 2019).
prostate carcinoma (continued). "HSD3B1 is the most common inherited link to prostate cancer mortality and mediates its effects by regulating steroid metabolism." (PMID 42294886, 2026). "While prior studies have primarily examined HSD3B1 c.1100 genotypes in prostate cancer outcomes and their impact on androgen deprivation therapy response, emerging evidence has extended their relevance to other hormone-driven cancers such as BC and EC." (PMID 40565184, 2025). "Regardless of its established role in androgen regulation and androgen signaling in prostate cancer, our findings suggest that tumors harboring the adrenal-permissive HSD3B1 exhibit profound differences in biological pathways." (PMID 40565184, 2025). "In this cohort study of US veterans undergoing treatment for prostate cancer at the VHA, the HSD3B1 CC genotype was associated with inferior outcomes." (PMID 38506808, 2024). "The objective of this study was to evaluate the differences in outcomes in men with prostate cancer based on HSD3B1 genetic status." (PMID 38506808, 2024). "Prostate cancer deaths were significantly higher in patients with the HSD3B1 CC genotype (14 of 402 patients [3.5%]) compared with the HSD3B1 AC (33 of 1970 patients [1.7%]) and AA genotypes (44 of 2915 participants [1.5%])." (PMID 38506808, 2024). "Non–prostate cancer mortality was similar in all HSD3B1 groups with 171 events in patients with the AA genotype (5.9%), 116 events (5.9%) in patients with the AC genotype, and 25 events (6.2%) in patients with the CC genotype." (PMID 38506808, 2024). "To investigate the prognostic significance of HSD3B1 among individuals likely to be receiving ADT, we evaluated outcomes by HSD3B1 status in a cohort of 619 men with prostate cancer who developed metastases." (PMID 38506808, 2024). "Genetic evidence from at least 10 prostate cancer cohorts on inheritance of the adrenal-permissive HSD3B1(1245C) allele demonstrates that increased metabolic flux through 3βHSD1 hastens androgen biosynthesis, progression to CRPC, and prostate cancer mortality." (PMID 36647826, 2023). "More importantly, in the CAF-CM environment, DHEA strongly activated AR-responsive genes in both prostate cancer cell lines; activation was attenuated by HSD3B1 siRNA." (PMID 37009898, 2023). "Our findings suggest that CAF-secreted glucosamine increases GlcNAcylation in prostate cancer cells, promoting Elk1-induced HSD3B1 transcription, which upregulates de novo intratumoral androgen synthesis to overcome castration." (PMID 37009898, 2023). "They found not only somatic mutations in HSD3B1 in multiple samples but also amplification and overexpression of HSD3B1 within prostate cancer cell lines and tissues from mCRPC patients." (PMID 37435458, 2022). "At a population level, the ‘adrenal-permissive’ SNP 1245(A→C) within HSD3B1 impacts prostate cancer outcomes." (PMID 37435458, 2022). "The role of HSD3B1 in the outcome of prostate cancer patients is an important landmark and example that a single APUC gene impacts the patient’s survival." (PMID 37435458, 2022). "Lastly, there are already currently available clinical and genetic tools and technologies to evaluate prostate cancer outcomes based on HSD3B1, SLCO2B1, and SRD5A2 genotype and their relationships to disease, which will guide future biomarker-driven treatment." (PMID 37435458, 2022). "What is the clinical impact of genetic variant in HSD3B1 when treated with androgen-deprivation therapy (ADT) and abiraterone for prostate cancer?" (PMID 30794306, 2019). "HSD3B1 has been shown to be a predictive biomarker for developing the castration resistance phase of prostate cancer upon androgen ablation therapies." (PMID 31638934, 2019). "Recently, the HSD3B1 status has been validated in prostate cancer patients as a robust molecular determinant to predict unfavourable response to ADT through testosterone synthesis." (PMID 29540470, 2018).
prostate carcinoma (continued). "Consistent with our clinical findings, a recent analysis of lipoprotein receptors in clinical prostate cancer showed that SRB1 mRNA correlated with HSD3B1 expression, and patients with high tumoral SRB1 levels had shorter progression‐free survival." (PMID 29540470, 2018). "As the rate-limiting step to androgen production, some inhibitors against the 3βHSD1 protein product for prostate cancer have been developed, and it has been found that the HSD3B1 CC genotype predicts worse outcomes in PC patients that receive hormone therapies." (PMID 40282446, 2025). "Importantly, in multiple clinical studies of prostate cancer patients, the HSD3B1 CC genotype predicts poor responses to hormone therapies and increased prostate cancer-specific mortality." (PMID 40565184, 2025). "Together, these studies are consistent with a model in which HSD3B1 expression and activity are largely present in peripheral tissues (including prostate cancer) without any major association between genotypes and circulating androgens." (PMID 39588946, 2025). "This suggests that the occurrence of lung metastases may be slightly greater in prostate cancer patients harboring the HSD3B1 c.1100 CC genotype." (PMID 40282446, 2025). "Together, these data indicate that HSD3B1 inheritance may drive a fundamental and mechanistic aspect of prostate cancer physiology that is pharmacologically actionable and reversible." (PMID 39286977, 2024). "Although the mutations in HSD3B1 have not been linked to any genetic diseases, it was reported that its SNPs are associated with breast and prostate cancers." (PMID 39415787, 2024). "Given the prognostic and potential therapeutic implications of HSD3B1 genetic status on outcomes, we used the large, ethnically diverse Million Veteran Program (MVP) data set to better inform our understanding of HSD3B1 genetic status in patients with prostate cancer." (PMID 38506808, 2024). "The cumulative incidence of PCSM at 5 years after diagnosis of prostate cancer was higher among patients with the HSD3B1 CC genotype (4.0%; 95% CI, 1.7%-6.2%) compared with the AC genotype (2.1%; 95% CI, 1.3%-2.8%) and AA genotype (1.9%; 95% CI, 1.3%-2.4%) (P = .02)." (PMID 38506808, 2024). "The slow conversion of 5-Adiol to T is indicative of the expected low activity of HSD3B1 which is considered a rate determining step in prostate cancer androgen metabolism which would also be consistent with its saturation kinetics displayed at high DHEA concentrations." (PMID 37772993, 2023). "This more active form of 3β-HSD1 is inherited in about half of all patients with CRPC and drives more aggressive clinical outcomes and shorter overall survival after treatment with ADT, thus providing genetic evidence for HSD3B1 in promoting resistance in clinical prostate cancer." (PMID 37009898, 2023). "In addition, cBioPortal analysis of a clinical data set showed that OGA mRNA levels inversely correlated with HSD3B1 mRNA levels in prostate cancer tissues." (PMID 37009898, 2023). "Overall, the story on the impact of allelic variations in HSD3B1 continues to be told across prostate cancers, other endocrine-driven diseases, or even malignancies in which we may not expect." (PMID 37435458, 2022). "In addition to the large body of literature examining the role of HSD3B1 genetics, work has been done to examine somatic alterations of HSD3B1 in prostate cancer through genomic tools." (PMID 37435458, 2022). "This could be biologically plausible if prostate cancers in men with the adrenal-permissive HSD3B1 genotype are more (nongonadal) androgen dependent compared with adrenal-restrictive HSD3B1 tumors, with the latter having a decreased capacity to use and depend on extragonadal androgens." (PMID 39286977, 2024).